ENSG00000281808
Gene: Small nucleolar RNA gene on chromosome 9 (136,726,748 to 136,726,879, reverse strand). Ensembl gene ENSG00000281808.
Gene Ontology:
Biological process: RNA processing
Cellular component: nucleolus
Homologues: Orthologues: rat LOC120102662 (77% identical), rat LOC120099020 (76% identical), rat LOC120101319 (76% identical), rat LOC120100413 (75% identical), rat LOC120100438 (74% identical), mouse Gm26184 (70% identical), rat LOC120094514 (70% identical), rat LOC120103343 (70% identical), rat LOC120103336 (69% identical), rat LOC120101330 (68% identical), rat LOC120096406 (66% identical), rat LOC120095452 (65% identical), and 7 more. Paralogues in human: SNORA17B (58% identical).